TBX5 (T-box transcription factor 5)
Diseases named in the same sentence as TBX5 in open-access papers (continued):
Sharing a sentence is not in itself a finding about the gene and the disease.
tumor (continued). "RT-qPCR was performed on 60 pairs of surgical specimens (tumor and adjacent non-tumor tissue samples) to examine the mRNA expression levels of TBX5." (PMID 26622790, 2015).
heart diseases (7 papers, 2012 to 2025). "Molecular network analysis and protein–protein interaction study indicated FOXO1 as strong transcription factor which interacts with other key genes like GATA4, CITED and TBX5 located on different chromosomes but associated with lethal heart disorders in PS." (PMID 30423812, 2018). "Therefore, our results demonstrate a strong association of TBX5 with heart diseases and further propose its important transcriptional regulatory role in the development of ICM for future mechanistic studies." (PMID 32423033, 2020).
cardiovascular diseases (5 papers, 2019 to 2025). "Here, eleven variants found in SALL4 and TBX5 were previously evaluated or associated with cardiac malformations or cardiovascular diseases 34,36–38." (PMID 31388035, 2019). "Further investigation of the CPC subpopulation (nestin+TBX5+SCA-1+) may enhance therapeutic strategies for cardiovascular diseases." (PMID 40869420, 2025). "Moreover, genes associated with human cardiovascular diseases, such as TNNT2, LMNA/C, TBX5, MYH7, ANKRD1, and NKX2.5, were also knocked-out by TALENs in human iPSCs to build cardiovascular disease models." (PMID 37626665, 2023). "It has been previously reported that malfunction of TBX5 could lead to several cardiovascular diseases during embryonic development and also during adulthood." (PMID 32423033, 2020). "The other T-box transcription factor, TBX5, is involved in cardiovascular development, and inactivating DNMT3A/3A2 contributes to cardiovascular disease." (PMID 35749276, 2022).
infection (4 papers, 2015 to 2021). The state of being infected such as from the introduction of a foreign agent such as serum, vaccine, antigenic substance or organism. "However, for MICFs, only about 0.1% cells were induced into cardiomyocyte-like cells after the infection of Gata4, Mef2c, and Tbx5." (PMID 33718351, 2021). "Among the GMT, Mef2c seems most rapidly targeted into nucleus, whereas Gata4 and Tbx5 were slower and observed in both the cytosol and nucleus by 3 hours of infection, however, by 4 hours of the infection time, most of injected proteins were localized into the nucleus." (PMID 26449528, 2015). "Only the Mef2c-Gata4-Tbx5 (MGT) and Mef2c-Tbx5-Gata4 (MTG) constructs, which have Mef2c in the first position, increase reprogramming efficiency compared to infection with three separate Gata4, Mef2c, and Tbx5 viruses." (PMID 28389873, 2017).
autosomal dominant disease (2 papers, 2012 to 2022). Autosomal dominant form of disease. "HOS is a highly penetrant autosomal dominant disease characterized by congenital malformations of the heart and upper limbs, which are two sites of Tbx5 expression." (PMID 23226307, 2012). "This is an autosomal dominant disease with a proximate cause of nonfunctional TBX5." (PMID 36214621, 2022).
skeletal dysplasia (1 paper, 2021). Any Mendelian diseases that affects growth and development of the skeleton. "Interestingly, all these genes except TBX5 are known to cause skeletal dysplasia in an autosomal recessive manner." (PMID 34149817, 2021).
TBX5 also shares sentences with these, for which no sentence is quoted: atrial septal defect (12 papers); Atrioventricular canal defect (4); Barrett esophagus (3); cardiac arrhythmia (3); DiGeorge syndrome (3); embryonal carcinoma (3); type 2 diabetes (3); atrioventricular septal defect (2); cardiac conduction disorders (2); Char syndrome (2); developmental delay (2); hypoplastic left heart syndrome (2); paroxysmal AF (2); rheumatoid arthritis (2); -hand” (1); acute myocardial infarction (1); ADULT syndrome (1); aortic stenosis (1); atrial septal aneurysm (1); autism (1); autosomal dominant hypocalcemia (1); Barth syndrome (1); bronchiectasis (1); calcific aortic valve disease (1); Cantu syndrome (1); carpal tunnel syndrome (1); chronic myeloid leukemia (1); Coffin-Lowry syndrome (1); conduction disorders (1); congenital heart malformation (1).
A further 51 diseases each share a sentence with TBX5 in 1 paper.